TNRC6C (trinucleotide repeat containing adaptor 6C)
Description:
Plays a role in RNA-mediated gene silencing by micro-RNAs (miRNAs). Required for miRNA-dependent translational repression of complementary mRNAs by argonaute family proteins. As scaffoldng protein associates with argonaute proteins bound to partially complementary mRNAs and simultaneously can recruit CCR4-NOT and PAN deadenylase complexes.
Synonyms: KIAA1582; FLJ20015
Tractability: PROTAC: its protein half-life has been measured.
Gene: Protein-coding gene on chromosome 17 (77,958,624 to 78,108,822, forward strand). Ensembl gene ENSG00000078687.
Subcellular location (Human Protein Atlas): Nucleoplasm
Pathways (Reactome):
Signal Transduction: Ca2+ pathway; Competing endogenous RNAs (ceRNAs) regulate PTEN translation; Estrogen-dependent gene expression; MAPK6/MAPK4 signaling; MTOR signalling; NR1H3 & NR1H2 regulate gene expression linked to cholesterol transport and efflux; Pre-NOTCH Transcription and Translation; Regulation of PTEN mRNA translation; TGFBR3 expression
Gene expression (Transcription): Post-transcriptional silencing by small RNAs; RUNX1 regulates genes involved in megakaryocyte differentiation and platelet function; Regulation of NPAS4 mRNA translation; Regulation of RUNX1 Expression and Activity; Transcriptional Regulation by VENTX
Cell-Cell communication: Regulation of CDH1 mRNA translation by microRNAs; Regulation of CDH11 mRNA translation by microRNAs
Cellular responses to stimuli: Oncogene Induced Senescence; Oxidative Stress Induced Senescence
Developmental Biology: Regulation of MITF-M-dependent genes involved in apoptosis
Disease: Nuclear events stimulated by ALK signaling in cancer
Immune System: Regulation of PD-L1(CD274) translation
Gene Ontology:
Molecular function: protein binding; nucleic acid binding; RNA binding
Biological process: miRNA-mediated post-transcriptional gene silencing; positive regulation of nuclear-transcribed mRNA catabolic process, deadenylation-dependent decay; positive regulation of nuclear-transcribed mRNA poly(A) tail shortening; miRNA-mediated gene silencing by inhibition of translation
Cellular component: cytosol; P-body
Genetic constraint (gnomAD): Loss-of-function variants: 21 observed, 150.57 expected, observed/expected ratio (o/e) 0.14, 90% interval 0.098 to 0.2. The upper end of that interval is the gene's LOEUF score, 0.2, which puts it in group 1 of 6, group 1 being the genes least tolerant of losing a copy. Missense variants: 1,983 observed, 2,138 expected, observed/expected ratio (o/e) 0.93, 90% interval 0.89 to 0.96. Synonymous variants: 810 observed, 821.84 expected, observed/expected ratio (o/e) 0.99, 90% interval 0.93 to 1.04.
Homologues: Orthologues: chimpanzee TNRC6C (99% identical), macaque TNRC6C (98% identical), guinea pig TNRC6C (89% identical), mouse Tnrc6c (89% identical), rat Tnrc6c (89% identical), dog TNRC6C (79% identical), pig TNRC6C (76% identical), tropical clawed frog tnrc6c (75% identical), rabbit TNRC6C (68% identical), zebrafish tnrc6c1 (54% identical). Paralogues in human: TNRC6A (44% identical), TNRC6B (34% identical), UBXN4 (6% identical), UBAC1 (6% identical), UBXN1 (5% identical).
Diseases named in the same sentence as TNRC6C in open-access papers:
TNRC6C is named in the same sentence as 13 diseases in open-access papers, as found by Europe PMC text mining. Sharing a sentence is not in itself a finding about the gene and the disease. The quoted sentences say what the papers report.
papillary thyroid cancer (2 papers, 2021). "in addition, CRLF1 is considered as a potential target gene of a tumor suppressor TNRC6C in papillary thyroid cancer." (PMID 34656128, 2021). "Our previous study found that trinucleotide repeat containing adaptor 6C (TNRC6C) may act as a tumor suppressor in papillary thyroid cancer (PTC)." (PMID 33564303, 2021).
depressive episodes (1 paper, 2024). "The most significant hits were for the number of manic episodes, with SLC13A3 as top gene in BP-I and TNRC6C in BP-II, followed by the number of depressive episodes, with MTSS1 as top gene in BP-I and DNAH14 in BP-II." (PMID 38865039, 2024).
fragile X syndrome (1 paper, 2022). A genetic syndrome caused by mutations in the FMR1 gene which is responsible for the expression of the fragile X mental retardation 1 protein. "The TNRC6 protein family, which includes, TNRC6C also has multiple reports in the literature of overlapping interactions with FMR1, the gene implicated in fragile X syndrome, which is one of the seven pathways prioritized in our analysis of the de novo variants." (PMID 35051175, 2022).
gastric cancer (1 paper, 2013). A primary or metastatic malignant neoplasm involving the stomach. "A Korean study of 2010 evaluated AGO1, AGO2, TNRC6A, TNRC6C, TARBP2 and XPO5 mutations in colorectal (CRC) and gastric cancers (GC), with or without microsatellite instability." (PMID 23586049, 2013).
non-small cell lung carcinoma (1 paper, 2018). A group of at least three distinct histological types of lung cancer, including non-small cell squamous cell carcinoma, adenocarcinoma, and large cell carcinoma. "The expression of TNRC6 proteins was down-regulated in gastric, colorectal and non-small cell lung cancers in previous studies as well as in PTC in our study, suggesting TNRC6C may be involved in the repression of some oncogenes through miRNA-dependent gene silencing." (PMID 30038597, 2018).
prostate adenocarcinoma (1 paper, 2022). "However, there was a weak negative correlation for TNRC6C in TGCT; TFDP1 in LAML; CDKN2C in prostate adenocarcinoma (PRAD); and CDKN2A in KIRC and THCA." (PMID 35911954, 2022).
cancer (4 papers, 2017 to 2022). A tumor composed of atypical neoplastic, often pleomorphic cells that invade other tissues. "As a whole, the ETS1, TNRC6B, and TNRC6C genes were thought to be preventive against tumors, while the remaining SRGs appeared linked to cancer risk." (PMID 35911954, 2022). "Additionally, some of the remaining genes in the FLC mRNA signature including, TMEM163, TNRC6C, and C10orf128 have yet to be extensively characterized in cancer." (PMID 28304380, 2017). "Also, HOPX was correlated with genes in a manner toward suppression of cancer cell progression; downregulation of TNRC6C, PAX8, TSHR, DYRK1A/B, and SLIT3 (pro-proliferation/migration), and upregulation of PCDH8/9, CDC42EP3/4/5, and TJP3 (anti-proliferation/migration)." (PMID 31666923, 2019).
tumor (3 papers, 2019 to 2023). "In conclusion, we demonstrated that TNRC6C functions as a tumor suppressor and is frequently downregulated in PTC." (PMID 33564303, 2021). "Regardless of the kind of mechanism, our findings support the tumor suppression role of TNRC6C in PTC, and it is important to find out the oncogenes targeted by it." (PMID 33564303, 2021). "After demonstrating the tumor suppressor role of TNRC6C on PTC, we further screened for potential target genes of TNRC6C." (PMID 33564303, 2021). "These genes were more likely to be the mediators through which TNRC6C played its tumor suppressor role." (PMID 33564303, 2021). "Given that TNRC6C played a tumor suppressor role, we speculated that TNRC6C might inhibit the development and progression of PTC through downregulating some oncogenic genes." (PMID 33564303, 2021). "Our study demonstrated that TNRC6C functions as a tumor suppressor in PTC and may serve as a useful therapeutic target and prognostic marker for PTC patients." (PMID 33564303, 2021).
TNRC6C also shares sentences with these, for which no sentence is quoted: cardiovascular disease (3 papers); manic episodes (1); metastasis (1); neurasthenia (1); Pheochromocytoma and Paraganglioma (1).